SNCAIP-AS3 (SNCAIP antisense RNA 3)
Synonyms: MGC32805
Gene: Long non-coding RNA gene on chromosome 5 (122,436,497 to 122,479,208, reverse strand). Ensembl gene ENSG00000250328.
Diseases named in the same sentence as SNCAIP-AS3 in open-access papers:
SNCAIP-AS3 is named in the same sentence as 2 diseases in open-access papers, as found by Europe PMC text mining. Sharing a sentence is not in itself a finding about the gene and the disease.
SNCAIP-AS3 shares sentences with these, for which no sentence is quoted: brain tumors (1 paper); glioma (1).